ATR (ATR checkpoint kinase)
Diseases named in the same sentence as ATR in open-access papers (continued):
Sharing a sentence is not in itself a finding about the gene and the disease.
latent infection (1 paper, 2016). "ATM, ATR, and DNA-PKcs as well as several downstream targets are modulated by KSHV during both latent infection and lytic replication, thus creating a favorable environment for virus persistence and viral replication." (PMID 27258263, 2016).
Liver toxicity (1 paper, 2024). "Liver toxicity was observed, first occurring in cohort A at gartisertib doses ≥700 mg twice weekly, which differed to previous studies of other ATR inhibitors." (PMID 38287179, 2024).
lymph node metastasis (1 paper, 2020). "The expression of p-ATR and M2-type TAMs were closely correlated each other and involved in TNM stage, lymph node metastasis and poor prognosis of the patients." (PMID 32917854, 2020). "Our results showed that the expression of p-ATR and CD68+CD206+ in EB virus-positive NPC was not correlated with age and sex, but with TNM stage and lymph node metastasis, suggesting that the high level of p-ATR and M2 is related to the poor prognosis of the patients." (PMID 32917854, 2020). "The levels of LMP1, p-ATR, and CD68+/CD206+ in NPC were not correlated with age and sex, but positively correlated with TNM stage and lymph node metastasis rate, which indicated a poor prognosis (*p < 0.05)." (PMID 32917854, 2020).
lymphoid leukemia (1 paper, 2024). A malignant lymphocytic neoplasm of B-cell or T-cell lineage involving primarily the bone marrow and the peripheral blood. "CRISPR‐Cas9 screens show that ATR is a dependency factor in 116 myeloid and lymphoid leukemia cells." (PMID 38520049, 2024).
meningioma (1 paper, 2018). A generally slow growing tumor attached to the dura mater.
metastatic prostate carcinoma (1 paper, 2024). A carcinoma that arises from the prostate gland and has spread to other anatomic sites.
Miller-Dieker syndrome (1 paper, 2011). "Previously, we have shown that Miller-Dieker Syndrome (MDS) and severe Isolated Lissencephaly Sequence (ILS+) patient-derived LBLs with RPA1 haploinsufficiency fail to activate the ATR-dependent G2-M checkpoint." (PMID 21901111, 2011).
MOPD type II (1 paper, 2012). "Given that all ATR–SS patients to date share consanguinity, there are limitations in defining the spectrum of clinical features conferred by ATR deficiency to support a clinical distinction between ATR–SS and related disorders such as MOPD type II and MGS as well as other sub-classes of SS." (PMID 23144622, 2012).
mucositis (1 paper, 2020). Mucositis is inflammation and damage of the mucous membranes lining the mouth and other parts of the gastrointestinal (GI) tract. "Notably, the incidence of mucositis was further increased by the addition of AZD6738, suggesting that patients treated with PARP and/or ATR inhibitor concomitantly with their radiotherapy course of treatment could be at higher risk for severe mucositis." (PMID 32546832, 2020).
oligodendroglioma (1 paper, 2022). A well-differentiated (WHO grade II), diffusely infiltrating neuroglial tumor, typically located in the cerebral hemispheres. "For oligodendroglioma, ATR inhibitors, IDH1 inhibitors, and pembrolizumab were recommended (n = 1 for each)." (PMID 35626060, 2022).
pituitary tumor (1 paper, 2020). A benign or malignant neoplasm affecting the pituitary gland.
Premature ovarian insufficiency (1 paper, 2025). Amenorrhea due to loss of ovarian function before the age of 40. "Recent studies identifying factors responsible for primary and premature ovarian insufficiency (POI) have reported either dramatic downregulation or non-functional variants of several DDR pathway members, such as BRCA1, RAD51, ATR, MSH4, MSH5, and FANC genes." (PMID 40148269, 2025).
promyelocytic leukemia (1 paper, 2014).
prostate (1 paper, 2012). "Our findings demonstrate that ATM/ATR inactivation is a crucial step in promoting androgen-induced genomic instability and prostate carcinogenesis." (PMID 23272087, 2012).
psoriasis (1 paper, 2011). An autoimmune condition characterized by red, well-delineated plaques with silvery scales that are usually on the extensor surfaces and scalp. "Thus, "Jak-STAT signaling pathway", "TNFR2 signaling Pathway" and "Role of BRCA1, BRCA2 and ATR in Cancer Susceptibility" are involved in the regulation of cellular responses to cytokines with the aim to providing an insight to the molecular mechanism involved in psoriasis." (PMID 21226955, 2011).
rhabdoid tumor (1 paper, 2025). An aggressive malignant embryonal neoplasm usually occurring during childhood. "Consequently, combined EZH2 and ATR inhibition improved therapeutic responses in diverse patient-derived epithelioid and rhabdoid tumors in vivo." (PMID 40794452, 2025).
Salmonella Infections (1 paper, 2026). Infections with bacteria of the genus SALMONELLA. "Recombinant typhoid toxin or Salmonella infection recapitulated LYZ and APOC3 secretion in cultured cells, which involved ATM/ATR-dependent DDRs and confirmed observations in typhoid fever." (PMID 41326716, 2026).
sarcopenia (1 paper, 2024). Progressive decline in muscle mass due to aging which results in decreased functional capacity of muscles. "We also observed enrichment of WIKI-pathway genes in cell cycle, as well as other pathways such as DNA IRdamage and cellular response via ATR, oxidative stress response and IL-4 signaling pathway in the sarcopenia group." (PMID 39026669, 2024).
skin telangiectasias (1 paper, 2023). "Interestingly, a germline heterozygous missense (c.6431A>G; p.Gln2144Arg) variant of ATR has been identified in several members of a family with a syndrome associating skin telangiectasias and anomalies of hair, eyebrows, tooth and nails." (PMID 36749285, 2023).
soft tissue tumors (1 paper, 2021). "ATR-inhibition may not demonstrate TMM-specific efficacy in soft tissue tumors; however, co-treatment of ATR inhibitors with other cytotoxic agents, such as gemcitabine, has proven to be broadly effective by increasing DNA damage in a TMM-independent manner." (PMID 34069193, 2021).
systemic lupus erythematosus (1 paper, 2022). An autoimmune multi-organ disease typically associated with vasculopathy and autoantibody production. "The results indicated that at both SLE and HC, the ATR pathway was up-regulated in EdU+ compared to EdU− B cells, while pH3+ cells exhibited increased pATR expression compared to pH3− cells only in lupus environment." (PMID 36306362, 2022).
testicular germ cell tumor (1 paper, 2019). A germ cell tumor arising from the testis. "In line with cell death critically depending on mtDNA-damage rather than nDNA-damage, apoptosis induction by cisplatin in testicular germ cell tumor cells does not require the nDNA-damage response mediating proteins ATM, ATR, or DNA-PK11." (PMID 31699970, 2019). "In line, cisplatin induced apoptosis even independent of nuclear DNA is illustrated by the fact that testicular germ cell tumor cells still undergo cisplatin induced apoptosis in the absence of key mediators of DNA damage response, such as ATM, ATR, or DNA-PK11." (PMID 31699970, 2019).
uveal melanoma (1 paper, 2023). A melanoma derived from melanocytes of the uveal tract. "We previously observed intron retention in POLD1 (exon 22–23), PNKP (exon 19–20), ATM, and ATR in uveal melanoma cell lines treated with PRT543 with concomitant loss in protein expression." (PMID 37861290, 2023).
cancer (802 papers, 2005 to 2026). A tumor composed of atypical neoplastic, often pleomorphic cells that invade other tissues. "Cancer cells tend to depend on ATR for the maintenance of genome integrity and the loss of ATR can downregulate the expression of other DNA repair proteins." (PMID 40647552, 2025). "Aberrant activation or dysregulation of the ATR pathway has been implicated in various human diseases, including cancer." (PMID 41392982, 2025). "ATM-deficient cancer cells cannot effectively signal DSBs, making them highly dependent on ataxia telangiectasia and Rad3-related protein (ATR) to manage replication stress and DNA damage." (PMID 41190241, 2025). "Ataxia telangiectasia mutated and Rad3 related (ATR) is a key regulator for the DNA damage response and a potential target to treat cancer." (PMID 39941729, 2025). "For instance, as noted, cancers with spliceosome gene mutations common in myelodysplastic syndromes and some leukemias accumulate R-loops and activate the ATR checkpoint kinase to cope with the ensuing replication stress." (PMID 40332372, 2025). "Cancer cells experiencing elevated replication stress or harbouring deficiencies in significant DNA repair pathways exhibit heightened susceptibility to ATR inhibitors, thereby enhancing the efficacy of genotoxic agents and promoting tumour cell eradication." (PMID 40256842, 2025). "Weaknesses in cancer cells that present DNA repair deficiencies or genomic instability can be exploited for synthetic lethality with Chk1/ATR and Chk2/ATM inhibitors." (PMID 40422251, 2025). "In this context, high-replication stress models, such as KRAS-mutated cancers, should be considered as relevant targets for ATR/Chk1 inhibition." (PMID 40422251, 2025). "It has also been implicated in modulating immune responses in other cancers, where ATR inhibition can promote T cell recruitment and enhance immune activation." (PMID 40674145, 2025). "A key finding of our study is the upregulation of the ATR signaling axis, indicating ongoing replication stress – a recognized hallmark of cancer-driven genome instability." (PMID 39910169, 2025). "For example, ATR is a serine/threonine kinase that is involved in sensing DNA damage and mutations in this kinase contribute to the genomic instability of cancer cells." (PMID 40103827, 2025). "Another striking example of induced synthetic lethality and antitumor immunity after ATR inhibition has been recently reported regarding Mismatch Repair (MMR) deficient cancer cells." (PMID 38474014, 2024). "Particularly, ATR is an essential protein with scarce loss-of-function mutations in cancer, while it has been observed that impaired ATR function in mouse models leads to tumorigenesis resistance." (PMID 38474014, 2024). "Cancer cells rarely display ATR mutations and are more susceptible to ATR inhibition since rely on ATR/Chk1 to safely progress through the cell cycle, to tolerate RS and to cope with genomic instability." (PMID 39492835, 2024). "Synthetic lethality resulting from combining ATM or ATR inhibition with the increased susceptibility of acid-exposed cancer cells to undergo DNA damages positions tumor acidosis as an attractive predictive biomarker for the clinical use of these drugs." (PMID 38366255, 2024). "Here, we review the main causes of RS in cancers as well as main therapeutic targets—ATR, CHK1, PARP and their inhibitors." (PMID 38279263, 2024).
cancer (continued). "ATR inhibition suppresses PD-L1 expression and mitigates PD-L1–PD-1 interactions, rendering cancer cells more susceptible to T-cell-mediated cytotoxicity." (PMID 39487895, 2024). "The roles of BRCA1, BRCA2, and ATR in cancer susceptibility, cyclins and cell cycle regulation, BRCA1-dependent Ub ligase activity, polyadenylation of mRNA, and Sonic Hedgehog receptor Ptc1 regulating cell cycle were the most enriched pathways in BioCarta." (PMID 39765633, 2024). "High expression levels of both HDAC8 and CHK1 or ATR was linked to poor overall survival in a pan-cancer dataset from TCGA." (PMID 39436709, 2024). "Analyzing cell cycle and apoptotic markers via FACS and Western blotting, we were able to show that apoptosis and S phase arrest contributed to the increased sensitivity of ATR-deficient cancer cells towards POLA1 inhibitors." (PMID 39128273, 2024). "We have demonstrated in our recent study that APE1 associates with ATR, ATRIP, and RPA to trigger the ATR-Chk1 DDR pathway activation in nuclear extract isolated from human cancer cells." (PMID 39112456, 2024). "The sensitivity of cancer cells to ATR inhibitors, which is caused by the overexpression of the oncogenic protein E1, is higher than that of other cell lines." (PMID 38910895, 2024). "As a result, it would be difficult to infer the clinical characteristics and implications of loss-of-function mutations of ATM/ATR in cancer patients." (PMID 38041093, 2023). "ES and targeted NGS of constitutive DNA allowed us to identify 2 potentially damaging variants of ATR in 2 MBC cases out of 164 subjects with suspicion of cancer predisposition." (PMID 36749285, 2023). "Concordant with this, the key kinase genes in DSB repair, ATM and ATR, are frequently mutated in various human cancers." (PMID 37373360, 2023). "In some cases, trials are taking advantage of ATM mutations that occur frequently across cancers and are synthetically lethal with ATR or DNA-PKcs deficiency." (PMID 38201511, 2023). "ATR is important for cell survival, particularly in the context of ATM mutations, making ATR a prospective target for cancer treatment." (PMID 36902170, 2023). "ATR haploinsufficiency, arising due to somatic mutations in one allele, is frequent in certain cancers, presenting therapeutic opportunities for POLH inhibition." (PMID 38068959, 2023). "Two additional possibly damaging variants of ATR were identified by cancer gene panel sequencing as part of their diagnostic work-up, both in female patients." (PMID 36749285, 2023). "PARP and ATR inhibitors were tested here because cancer cells with ATM deficiency are sensitive to PARP and ATR inhibition." (PMID 36797243, 2023). "The loss of G1 control, a common feature in cancer, and increased RS in tumours both result in dependency on ATR, CHK1 and WEE1 signalling, making these kinases attractive targets for cancer therapy." (PMID 36606678, 2023). "In fact, ATR inhibitors have been reported to act in a synthetic lethal way in ARID1A-deficient cancer." (PMID 36123603, 2022). "Recent results from phase I clinical studies have demonstrated durable anti-tumor activity of ATR inhibitors in advanced cancers with either deleterious ATM mutations or loss of ATM protein expression." (PMID 35954206, 2022). "For example ataxia-telangiectasia-mutated (ATM) and Rad3-related protein kinase (ATR) is a key regulator of the DNA damage response and ATR inhibitors are of interest to cancer researchers to potentiate the effects of radiotherapy." (PMID 35998812, 2022).